TNF (tumor necrosis factor)
Diseases named in the same sentence as TNF in open-access papers (continued):
Sharing a sentence is not in itself a finding about the gene and the disease.
Insulin resistance (continued). "The reduction in α2,3-sialylation on adipocyte membrane proteins, associated with lower ST3GAL6 expression, occurred after TNF-α treatment to induce insulin resistance." (PMID 41301440, 2025). "TNF-α, one of the most common inflammatory factors, has been closely linked to insulin resistance in animal models." (PMID 41293068, 2025). "Given the fact that insulin resistance and the autoimmune response in pancreatic β-cells have been associated with increased levels of TNF-α, its role in the pathogenesis of NL has also been explored." (PMID 40277935, 2025). "Chronic inflammation, driven by T2D-associated hyperglycemia and insulin resistance, induces pro-inflammatory cytokines such as tumor necrosis factor (TNF)-α and interleukin (IL)-6, activates nuclear factor (NF)-κB, and generates reactive oxygen species." (PMID 41226058, 2025). "Bariatric surgery reduces visceral adiposity, which is strongly associated with insulin resistance, and leads to decreased secretion of pro-inflammatory cytokines like tumor necrosis factor-alpha (TNF-α) and interleukin-6 (IL-6)." (PMID 40626220, 2025). "Studies have shown that tumor necrosis factor-alpha (TNF-α) and C-reactive protein levels at 24–28 weeks of gestation are strongly correlated with pregnancy-associated insulin resistance, making them potential inflammatory biomarkers for GDM management." (PMID 40678778, 2025). "Insulin resistance is usually associated with high levels of inflammatory and oxidative biomarkers and mediators namely, tumor necrosis factor (TNF)-α, plasminogen activator inhibitor-1 (PAI-1), C-reactive protein (CRP), interleukin-6 (IL-6)." (PMID 40056319, 2025). "Patients with a TNFα polymorphism in its gene’s promoter (−238 G/A) had a higher occurrence of insulin resistance and impaired glucose tolerance." (PMID 40985048, 2025). "Exercise reduces the levels of pro‐inflammatory biomarkers such as C‐reactive protein (CRP), interleukin‐6 (IL‐6) and tumour necrosis factor‐alpha (TNF‐α), which are associated with insulin resistance and cardiovascular diseases." (PMID 40371883, 2025). "Excessive lipid storage predisposes individuals to insulin resistance, as large dysfunctional adipocytes exhibit reduced insulin sensitivity and secrete pro-inflammatory cytokines (e.g., TNF-α, IL-6), further exacerbating metabolic dysregulation." (PMID 40218884, 2025). "VAT secretes pro-inflammatory adipokines (e.g., IL-6, TNF-α) that induce insulin resistance (a lung cancer risk factor and impair mitochondrial function." (PMID 41048699, 2025). "Physical activity also stimulates muscle-derived IL-6 release, proportional to muscle mass and exercise intensity and decreases TNF-α levels and reduces insulin resistance risk." (PMID 41515940, 2025). "TNF-α, a key inflammatory cytokine, is strongly linked to insulin resistance, glucose metabolism disorders, and abnormal lipid metabolism." (PMID 41244040, 2025). "Chronic low-grade inflammation, characterized by elevated cytokines like IL-6 and TNF-α, is a hallmark of hyperlipidemia and insulin resistance." (PMID 40509408, 2025). "Increased concentrations of pro-inflammatory cytokines, specifically IL-6, TNF-α, and IL-1, have been repeatedly associated with frailty, cognitive deterioration, atherosclerosis, insulin resistance, and neurodegenerative disorders in the elderly." (PMID 40507795, 2025). "The results of logistic regression analysis indicate that TNF-α is more strongly associated with abdominal obesity, while IL-6 shows stronger connections with insulin resistance and dyslipidemia." (PMID 40137151, 2025). "IL‐13 neutralizes pro‐inflammatory cytokines (such as TNF‐α and IL‐6), which were associated with the development of insulin resistance in T2DM." (PMID 39355932, 2025). "Son and Wu (2019) also shed light on the remarkable ability of EWH to reverse insulin resistance associated with TNF‐α in skeletal muscle cells." (PMID 40761488, 2025).
Insulin resistance (continued). "TNF-α directly causes insulin resistance in skeletal muscle and adipose tissue by inhibiting the tyrosine phosphorylation of insulin receptor substrate 1 (IRS-1) and activating the IKK and JNK pathways." (PMID 40661082, 2025). "Sarcopenia is often associated with chronic low-grade inflammation, insulin resistance, and oxidative stress, while visceral adiposity contributes to these processes through the secretion of pro-inflammatory adipokines such as IL-6 and TNF-α." (PMID 41245877, 2025). "Research has shown that insulin resistance is closely associated with the excessive production of pro-inflammatory cytokines, including IL-6, IL-1β, and TNF-α, which contribute to disease progression." (PMID 40136627, 2025). "In terms of clinical mechanisms, reducing inflammatory markers such as CRP and TNF-α can significantly alleviate systemic inflammation, thereby decreasing the risk of complications like vascular dysfunction and insulin resistance." (PMID 40123937, 2025). "Chronic inflammation is a common feature of both conditions, with inflammatory cytokines like tumor necrosis factor-alpha (TNF-α) and interleukin-6 (IL-6) promoting insulin resistance, a hallmark of T2D." (PMID 41007787, 2025). "Dysregulated TNF-α signaling has been implicated in numerous conditions such as autoimmune disorders, insulin resistance, systemic rheumatic diseases, cancer, and severe manifestations of SARS-CoV-2 infection." (PMID 41268160, 2025). "Among the genes implicated in T2DM, TNF-α, a key pro-inflammatory cytokine, plays a critical role in insulin resistance and systemic inflammation." (PMID 41268160, 2025). "Inflammatory mediators, such as TNF-α and IL-6, interfere with normal insulin function, ultimately leading to the onset of insulin resistance and an increased risk of developing prediabetes." (PMID 40997104, 2025). "These metabolic effects have been linked to increased oxidative stress, insulin resistance, and enhanced production of proinflammatory mediators such as TNF-α, IL-6, and CRP." (PMID 40724965, 2025). "It has been well documented that TNF-α is associated with glucose metabolism and insulin resistance in both animals and humans." (PMID 39803918, 2025). "We observed that PA increased several inflammatory genes like IL1B and TNF, which are closely associated with dysfunction of pancreatic islets, adipose, and skeletal muscle related to insulin resistance and hyperglycemia." (PMID 40068774, 2025). "The elevated secretion of TNF-α and other cytokines from these cells perpetuates insulin resistance, linking PsA to increased susceptibility to type 2 diabetes mellitus." (PMID 40137170, 2025). "For instance, TNF-α has been implicated in promoting insulin resistance and activating inflammatory pathways, including nuclear factor-B and c-jun N-terminal kinase, that lead to hepatocyte injury." (PMID 41347218, 2025). "These factors make preadipocytes more susceptible to the anti-adipogenic and insulin resistance-inducing effects of TNF-α, further exacerbating metabolic dysregulation." (PMID 41574186, 2025). "The blockade of TNF-α has been linked with enhancement of hepatic damage markers and decrease in insulin resistance which supports the crucial role in the pathogenesis of MASLD." (PMID 41220583, 2025). "TNF-α overexpression in the adipose tissue of obese individuals and obese mice causes peripheral insulin resistance." (PMID 40362446, 2025). "The chronic inflammatory state, driven by the secretion of tumor necrosis factor α (TNFα) and other pro-inflammatory cytokines, disrupts insulin signaling pathways, causing insulin resistance." (PMID 41471111, 2025). "TNF-α is a further parameter to examine when considering the damage caused by insulin resistance in the cell." (PMID 40729004, 2025). "MPs activate pro‐inflammatory pathways, such as NF‐κB and MAPK, which lead to increased production of cytokines, such as IL‐6 and TNF‐α—factors implicated in insulin resistance as well as carcinogenesis." (PMID 41498107, 2025).
Insulin resistance (continued). "TNF-α levels have been associated with insulin resistance in obesity, aging, sepsis, and muscle damage." (PMID 39035597, 2024). "The DM-linked pathways identified (i.e., insulin resistance, adherens junctions, metabolic processes, and the IL-17, cAMP, relaxin, TNF, and AGE-RAGE signaling pathways involved in diabetic complications) were used to construct the target-pathway (TP) network." (PMID 39458839, 2024). "Chronic inflammation in tissues is typically the primary cause of insulin resistance, which results in the secretion of pro-inflammatory cytokines such as tumor necrosis factor alpha (TNF-α) or IL-6 by inflammatory cells." (PMID 38720885, 2024). "The pro-inflammatory cytokine TNF-α is linked to obesity, inflammation, and insulin resistance due to its crucial contribution to adipocyte metabolic dysregulation." (PMID 38963109, 2024). "Specifically, PTP1B-deficient rats exhibit decreased TNF-α-dependent insulin resistance and increased insulin sensitivity in adipose tissue and skeletal muscles." (PMID 38431555, 2024). "It is widespread, common knowledge that the activity of M1 macrophages produce interferons and the pro-inflammatory TNFα and IL-6, which are closely associated with the progression and severity of insulin resistance." (PMID 39200288, 2024). "IL-6 is susceptible to production induced by TNF-α, which can worsen hepatic steatosis, insulin resistance, and inflammation in the pathogenesis of NAFLD, thereby facilitating the onset and progression of the disorder." (PMID 39161898, 2024). "Tumor necrosis factor (TNFα) is associated with insulin resistance and induces inflammatory cytokines." (PMID 39411175, 2024). "Elevated ceramide levels have been linked to insulin resistance and TNF-α-induced insulin desensitization." (PMID 39590846, 2024). "Increased levels of TNF-α and IL-6 cause the activation of inflammatory processes; additionally, both cytokines are insulin-resistance inducers at the peripheral level and hepatic level, respectively." (PMID 39125666, 2024). "Genetic polymorphisms in the TNF-α and IL-10 genes play a crucial role in the development of insulin resistance, type 2 diabetes mellitus (T2DM), and its complications." (PMID 39596058, 2024). "Low adiponectin levels were also associated with an increased risk of insulin resistance, and TNF-α is a strong inhibitor of adiponectin promoter activity." (PMID 38905235, 2024). "This suggests that FhHDM-1 downregulated apoptotic pathways, pathways associated with inflammation (i.e., TNF and insulin resistance), and more specifically, inflammatory pathways associated with diabetes." (PMID 39022651, 2024). "Elevated plasma concentrations of inflammatory mediators such as tumor necrosis factor α and interleukin-6 are linked to insulin resistance and T2DM." (PMID 39062034, 2024). "Among these, leptin, adiponectin, CRP, TNF-α, and resistin are closely associated with the occurrence and development of insulin resistance." (PMID 40302954, 2024). "NODAT exhibits a strong connection with visceral obesity, leading to the generation of inflammatory cytokines such as interleukin-6 and tumor necrosis factor-α, along with reduced levels of adiponectin associated with insulin resistance." (PMID 38610694, 2024). "Adiponectin, secreted by adipocytes, has been implicated in the development of insulin resistance; our data showed that TNF-α-treated spheroids downregulated the relative mRNA expression of adiponectin and reduced the amount of secreted protein." (PMID 38820505, 2024). "Chronic low-grade inflammation, mediated by pro-inflammatory cytokines such as TNF-α and IL-6, has been implicated in the pathogenesis of insulin resistance." (PMID 39211341, 2024). "Previous studies have shown that increased TNF-α and macrophage levels in the adipose tissue (AT) of obese mice and humans are associated with insulin resistance." (PMID 38750502, 2024).
Insulin resistance (continued). "TNF-α has been implicated in the pathogenesis of insulin resistance and the initiation of the development of T2DM." (PMID 39408723, 2024). "TNF-α and IL-6 are pro-inflammatory cytokines secreted from the peri-visceral fat; their effect is linked to insulin resistance, atherosclerosis, and endothelial dysfunction." (PMID 39204094, 2024). "The development of insulin resistance is closely linked to dyslipidemia and elevated levels of pro-inflammatory cytokines such as TNF-α and IL-6." (PMID 39596058, 2024). "The degree of insulin resistance was associated with biomarkers, such as adiponectin, tumor necrosis factor-α, branched-chain amino acids, the visceral fat area, and the dose of insulin required for glycemic control." (PMID 38905235, 2024). "TNF‐α is a pro‐inflammatory cytokine implicated in the pathogenesis of insulin resistance and is known to induce inflammation in placental tissue." (PMID 39230472, 2024). "Insulin resistance is also associated with increased levels of pro-inflammatory cytokines, TNF alpha and IL-6." (PMID 39457712, 2024). "TNF-α promotes insulin resistance, causes hyperandrogenism, and is involved in follicular development; hence, it has been implicated in the pathophysiology of PCOS." (PMID 38540173, 2024). "In mouse models, the depletion of SAT has been associated with increased insulin resistance, elevated levels of TNF-α, and induced metabolic deterioration." (PMID 38185678, 2024). "Increased levels of IL-1β, IL-6, and TNF-α have been observed in adipose tissue and serum of obese patients, which is associated with insulin resistance in humans and obese mice exposed to HFD." (PMID 39274918, 2024). "Monocyte chemotactic protein (MCP)-1, tumor necrosis factor (TNF)-α, interleukin (IL)-1, IL-6, and IL-8 have all been linked to insulin resistance." (PMID 38732619, 2024). "Proinflammatory cytokines produced by immune cells and secreted by the adipose tissue, such as TNF-α, IL-4, and IL-6, stimulate obesity-associated diseases, including insulin resistance, dyslipidemia, and cardiovascular diseases." (PMID 39204167, 2024). "It has been proposed that a deficiency of TNFα in high-fat-diet-fed mice protects against insulin resistance and improves glucose metabolism." (PMID 39596898, 2024). "Leptin, PAI-1, TNFα, and IL-6 levels are elevated in obese individuals and are associated with insulin resistance." (PMID 38317257, 2024). "Insulin resistance has been accredited to adipose tissue activation linked with an elevated release of inflammatory cytokines such as TNF-α and IL-6." (PMID 38962295, 2024). "It has been shown to reduce the levels of pro-inflammatory cytokines such as IL-1β, IL-6, and TNF-α, which are associated with insulin resistance and chronic inflammation in diabetes." (PMID 39092264, 2024). "TNF-α, which is overexpressed by adipocytes under conditions of insulin resistance and the hypertrophy of adipose cells, causes insulin resistance by interfering with the transmission of the insulin signal and activating inflammation processes." (PMID 39125666, 2024). "Increased TNF-α levels have also been demonstrated to cause insulin resistance by affecting insulin signaling and glucose absorption in vivo, similarly to IL-6." (PMID 38390960, 2024). "Insulin resistance is caused, among others, by tumor necrosis factor alpha (TNF-α), the increased production of which is observed in people with excessive adipose tissue." (PMID 38612580, 2024). "TNF-α is an inflammatory cytokine and an important factor that exacerbates insulin resistance and causes dyslipidemia." (PMID 39456928, 2024). "TNF-α and IL-6 have been associated with impaired intracellular insulin signalling, potentially leading to insulin resistance and further diabetes complications." (PMID 38614881, 2024). "TNF-α also plays a crucial role in the processes underlying innate or adaptive immune responses and insulin resistance and can be affected by short-term exposure to air pollutants." (PMID 38494707, 2024).
Insulin resistance (continued). "As a result of periodontitis, inflammatory markers, such as interleukins and TNF-α, can be released into the bloodstream, which can cause insulin resistance before long and affect the destruction of beta cells in the pancreas, disrupting glucose metabolism." (PMID 39767238, 2024). "Elevated levels of pro-inflammatory cytokines such as Interleukin-6 (IL-6) and tumor necrosis factor-alpha (TNF-α) are implicated in insulin resistance by disrupting the insulin signaling pathway." (PMID 39691364, 2024). "This was somewhat surprising given that the faLA group had the highest levels of pro-inflammatory marker TNF-α in adipose tissue, and pro-inflammatory markers such as TNF-α are associated with insulin resistance and systematic inflammation." (PMID 38732558, 2024). "Previous studies have shown that PC is associated with improved insulin resistance and abnormal lipid accumulation and inhibits the synthesis and release of multiple inflammatory factors, such as IL-1β and TNF-α." (PMID 39403583, 2024). "TNF-α and IL-6, two main adipose-tissue-derived inflammatory cytokines, have been implicated in the induction of insulin resistance." (PMID 37893164, 2023). "One of the most important inflammatory mediators that has been implicated in the development of insulin resistance (which is central to the development of type 2 diabetes) is TNF-α which is also involved in the pathogenesis of malaria." (PMID 37215099, 2023). "Increased levels of inflammatory markers (IL-6 and TNF-α) in the body are associated with an increased risk of insulin resistance and cardiovascular disease." (PMID 36976940, 2023). "TNFα is a pro-inflammatory cytokine which rises during pregnancy and is also associated with insulin resistance outside of pregnancy in obesity, aging and sepsis." (PMID 38288471, 2023). "Several adipokine-associated molecules, such as tumor necrosis factor-alpha, interleukin-1β, and interleukin-6, have been linked to increased insulin resistance, inflammation, and fat accumulation." (PMID 37762592, 2023). "TNF-α plays an important role in the pathogenesis of malaria and has also been implicated in the development of insulin resistance which contributes to the development of type 2 diabetes." (PMID 37215099, 2023). "TNF-α causes insulin resistance by stimulating serine phosphorylation of insulin receptor substrate-1(IRS-1) and interfering with the functions of β cells." (PMID 37346347, 2023). "The health of the adipose tissue and its role in driving inflammation and insulin resistance is associated with other markers, including IL-1, IL-6, and TNF-alpha." (PMID 37108980, 2023). "Overexpression of adiponectin, leptin, and TNF-α is a major factor increasing the risk of liver fat accumulation, insulin resistance, pancreatic beta cell dysfunction, and fibrosis." (PMID 37298268, 2023). "The authentic interplay between our iPSC-Heps and M1 iPSC-Macs allowed us to identify TNFα and IL1β as the cytokines causing inflammation and insulin resistance in iPSC-Heps." (PMID 37400454, 2023). "Inflammation and insulin resistance are closely linked, and inflammatory cytokines such as TNF-α, IL-6, IL-1 and IL-8 can inhibit insulin signaling by multiple mechanisms." (PMID 36860845, 2023). "Multiple cell types including neutrophils in COPD patients produce large amounts of tumor necrosis factor-α (TNF-α), which is one of the factors causing insulin resistance." (PMID 37238649, 2023). "More recently, it has been reported to produce proinflammatory expression in genes, including the CD68 and tumor necrosis factor-alpha (TNF-α) genes in adipose tissue, and is associated with insulin resistance and hyperlipidemia." (PMID 38203349, 2023). "A high-fat diet is associated with metabolic endotoxemia caused by serum LPS, resulting in obesity and insulin resistance, and high serum LPS enhances TNF-α and inhibits insulin signals." (PMID 36900540, 2023).